ELF3 (E74 like ETS transcription factor 3)
Diseases named in the same sentence as ELF3 in open-access papers (continued):
Sharing a sentence is not in itself a finding about the gene and the disease.
tumor (continued). "Erastin-mediated inhibition of SLC7A11 induced ferroptosis in cells with ELF3 overexpression and PTEN deficiency and thus inhibited cell colony formation and tumor development." (PMID 39695109, 2024). "First, we analyzed the DNA methylation of ELF3 in tumor tissues of patients with NPC using methylation-specific PCR." (PMID 39219440, 2024). "The findings suggest that the DLEU2/miR-212-5p/ELF3 axis plays a crucial role in mediating the anti-tumor effects of Huaier." (PMID 38169645, 2024). "By visualizing the expression of MUC1 and ELF3 genes in their spatial locations in the EC, we found that these two genes were mainly enriched in the tumor region." (PMID 38517922, 2024). "Experimental studies have demonstrated that re‐introducing ELF3 expression in OC cell lines with low endogenous expression inhibits cell proliferation both in vitro and in vivo, supporting its tumour‐suppressive role." (PMID 38520216, 2024). "Correlation analysis in both human HCC tumor samples and in the NRasV12+Myr-AKT proto-oncogenes-driven HCC tumor mouse model likewise found ELF3/Elf3 and SPINK1/Spink1 expression to positively correlate." (PMID 38030644, 2023). "In circulating tumor cells and in patient tumor biopsies, too, expression levels of ELF3 and ZEB1 were anti-correlated." (PMID 36864480, 2023). "ELF3 is upregulated in tumor cells under the secretion of immunoinfiltrating inflammatory cytokines, which activates the PI3K/Akt/NF-κB pathway and up-regulates the expression of proliferative and anti-apoptotic genes." (PMID 37671151, 2023). "The overexpression of miR-455-3p or ELF3 knockdown was shown to be capable of reversing the anti-tumor effects of LINC00472 in OSCC." (PMID 35258410, 2022). "While ELF3, as the epithelial cell-specific transcription factor, is a documented tumor suppressor in many epithelial tumors yet displays oncogenic properties in others, was marked in CTB_invasion1 cells." (PMID 36420138, 2022). "The function of LINC00472 appears to be dependent on up-regulating ELF3 (a tumor suppressor) expression by blocking miR-455-3p." (PMID 35258410, 2022). "First, ELF3 was described as a tumour repressor of PCa by interfering with androgen receptor (AR) DNA binding, resulting in repression of AR target genes, which are drivers of PCa." (PMID 35472129, 2022). "As transcription factors belonging to the ETS family, ELF3 participates in autoimmune and tumor neogenesis." (PMID 35284413, 2022). "Knocking down ELF3 in the LNCaP cell line model led to increased cell migration and proliferation, whilst overexpression of ELF3 in an LNCaP xenograft model repressed tumour growth." (PMID 35472129, 2022). "In contrast, the second key study described ELF3 as an oncogenic driver of PCa, based on the detection of high levels of ELF3 mRNA in patient data sets and elevated expression of ELF3 protein in 63% of 207 tumours." (PMID 35472129, 2022). "Next, qRT-PCR assays were conducted for detecting LINC00472’s RNA expression, miR-455-3p, and ELF3 (left) in tumor tissues." (PMID 35258410, 2022). "By performing pseudotime trajectory, we found that ELF3 was among the most upregulated genes in more advanced tumor cells." (PMID 33144684, 2021). "In particular, ELF3 was also reported to be a potential biomarker for detecting circulating tumor cells in NSCLC and has been suggested to be a prognostic biomarker in lung adenocarcinoma (LUAD)." (PMID 34830169, 2021). "To address the role of ELF3 in LUAD, we used the TCGA LUAD data (n = 515) and found that ELF3 was upregulated in tumor samples compared to the normal lung tissues." (PMID 33144684, 2021). "We found that ELF3 was highly expressed in all the tumor tissues compared to the matched normal samples." (PMID 33144684, 2021). "Since other cell types in TME, especially immune cells, also highly express NF-κB target genes, we decided to use LUAD cell lines A549 and NCI-H1975 to further investigate the function of ELF3 in tumor cells." (PMID 33144684, 2021).
tumor (continued). "We first confirmed the upregulation of ELF3 at protein level in the tumor tissues compared to the normal lung tissues." (PMID 33144684, 2021). "Taken together, pro-inflammatory cytokine IL1B in the tumor microenvironment can upregulate ELF3 in LUAD tumor cells, which augments the activation of NF-κB pathway to favor tumor cell survival and growth." (PMID 33144684, 2021). "We investigated the role of an important modulator ELF3 in mediating interaction between TAMs and tumor cells in LUAD." (PMID 33144684, 2021). "Subgroup 2 highly expressed E74-Like Factor 3 (ELF3), the expression of which is usually elevated in PCa for tumor growth." (PMID 33032611, 2020). "Although ELF3 has been reported to be a tumor suppressor in many epithelial cancer types, its function has also been observed to be highly cell-type specific with reported oncogenic roles in LUAD80." (PMID 33083012, 2020). "ELF3, a documented tumor suppressor in many epithelial tumors, displays strong prognostic value in LUAD and has been proved to be an oncogene and putative therapeutic target in LUAD27." (PMID 33070167, 2020). "The elevated expression of ELF3 has a positive correlation with larger tumor size and poor prognosis." (PMID 33585247, 2020). "The epithelial cell-specific transcription factor ELF3 is a documented tumor suppressor in many epithelial tumors yet displays oncogenic properties in others." (PMID 31780666, 2019). "ELF3 expression was required for tumor growth and a pan-cancer expression network analysis supports its subtype and tissue specificity." (PMID 31780666, 2019). "The effect of ELF3 inhibition on tumor growth was once again assessed using clonal populations of cells (A549 shRNA-1, and isogenic control) injected into the flanks of NOD-SCID mice (n = 24)." (PMID 31780666, 2019). "The effect of ELF3 inhibition on tumor growth was examined in vivo using a xenograft model of HCC827 shELF3 (shRNA-1) cells and isogenic controls (n = 12 NOD-SCID mice)." (PMID 31780666, 2019). "This suggests strong selective pressure maintains ELF3 expression throughout xenograft tumor growth." (PMID 31780666, 2019). "ELF3 was discovered more than 20 years ago, and our understanding of its functions in tumor cells has grown exponentially over the past decade." (PMID 29523781, 2018). "Previous studies have revealed that ELF3 plays important roles in invasion, migration, and tumor progression; however, recent evidence indicated that ELF3 overexpression suppressed EMT in ovarian cancer." (PMID 29523781, 2018). "The effect of ELF3 on tumor metastasis was assessed in immunocompromised male BALB/c mice (n = 6), using the splenic injection model." (PMID 29523781, 2018). "Reconstruction experiments were used to optimise immunomagnetic enrichment and RT-PCR detection of circulating tumor cells using four markers (ELF3, CK19, EGFR and EphB4)." (PMID 19961621, 2009). "In the Her2 subtype, higher ELF3 expression is also related to shorter overall survival, consistent with previous reports that as a Her2 target gene, ELF3 may help promote tumor invasion." (PMID 41498327, 2026). "ELF3 acts as an oncogene or a tumor suppressor in different contexts." (PMID 41425714, 2025). "Conversely, TQ treatment resulted in the downregulation of several genes overexpressed in GBM cells, including potential oncogenes like AEBP1, MIAT, GHR, LMO1, ELF3, and genes involved in tumor proliferation and migration such as EPHA4, COL3A1, PCDH10, ROBO1, ADAMTS5, PCDH18, ST8SIA1." (PMID 39874307, 2025). "Taken together, these results illuminate the mechanism underlying Huaier's anti-tumor effects via the DLEU2/miR-212-5p/ELF3 signaling pathway, which offers novel insights into the anti-tumor effects of Huaier and constitutes a promising therapeutic target for the treatment in NSCLC." (PMID 38169645, 2024).
tumor (continued). "Meanwhile, genes positively correlated with CLDN4 in expression, such as ANXA2, EZR and ELF3, were also discovered in our study, which were also reported to play a role in tumour progression and might explain the role of CLDN4 in a way." (PMID 38629624, 2024). "Therefore, we planned to conduct relevant follow-up studies to continue exploring the relevant mechanisms of how ELF3 regulates tumor occurrence and development." (PMID 39695109, 2024). "E74 Like ETS Transcription Factor 3 (ELF3) has key roles in tumor progression and embryogenesis." (PMID 38730433, 2024). "The methylation level of ELF3 in NPC tumor tissues was lower than that in control tissues." (PMID 39219440, 2024). "However, in tumor tissues formed by C666-1 cells with both ELF3-KD and MUC16-OE, an impaired antitumor response of T cells was observed." (PMID 39219440, 2024). "HIDDEN cell effects on basal cells might occur via paracrine activities that create a pro-tumor microenvironment, and particularly in severely dysplastic lesions where ELF3+ HIDDEN cells appear to expand downwards into the basal layer." (PMID 37031202, 2023). "Under the effect of immune infiltrating inflammatory cytokines (such as IL1B), ELF3 in tumor cells was up-regulated, thereby activating PI3K/Akt/NF- κB pathway, and up-regulating the expression of proliferation and anti-apoptosis genes, such as BCL2L1 and CCND1." (PMID 37671151, 2023). "Multiplex staining also confirmed co-localization of SPINK1 and ELF3 in human HCC tumor samples." (PMID 38030644, 2023). "Hence, the interplay between ELF3, EMT and stemness appears to be context-specific, reminiscent of recent observations associating various stages of EMT with enhanced tumor-initiation potential in many cancer types." (PMID 36864480, 2023). "The present study found that ELF3 was down-regulated in OSCC tumor tissues." (PMID 35258410, 2022). "The proposed mechanism by which ELF3 might drive tumour progression was through a positive feedback loop with NFkappaB, which upregulates ELF3 in model systems." (PMID 35472129, 2022). "The results show that miR-455-3p/ELF3 mediates the anti-tumor function of LINC00472 in OSCC." (PMID 35258410, 2022). "High expression of ELF3 also favors tumor growth through activation of MAPK and NF-κB pathway." (PMID 33144684, 2021). "We hypothesize that IL1B released from TAMs triggers elevated expression of ELF3 in LUAD tumor cells." (PMID 33144684, 2021). "The tumor-specific SE-associated genes were enriched in important pathways, such as chordate embryonic development (RUNX2, FOXA1), regulation of cell adhesion (RUNX1, SOX2 and VEGFA), and epithelial cell differentiation (SOX9, ELF3)." (PMID 34001209, 2021). "We inferred some copy number gains of CCND1 on chromosome 11, which may contribute to its overexpression in some tumor cells in addition to transcriptional regulation mediated by ELF3." (PMID 33144684, 2021). "Furthermore, TCGA LUAD samples with higher tumor cell purity exhibited higher ELF3 expression, consistent with overexpression in tumor cells." (PMID 31780666, 2019). "Our discovery of a region of focal amplification at the ELF3 locus, coupled with our findings that ELF3 knockdown is highly selected against in a polyclonal tumor growth model and completely abrogates tumor growth in a clonal setting highlights the importance of this oncogene." (PMID 31780666, 2019). "It is evident that ELF3 is capable of regulating oncogenic phenotypes; however, these results indicate the functional importance of ELF3 may arise during a later stage of tumor development or on a background of further genetic alterations." (PMID 31780666, 2019). "Nevertheless, we establish the requirement of ELF3 expression for tumor initiation and growth." (PMID 31780666, 2019). "ELF3 gene plays a major role in tumor proliferation, invasion, and metastasis." (PMID 30832724, 2019).
tumor (continued). "In addition to these mechanistic studies, we show that ELF3 gene-expression across tumour panels is inversely correlated to markers of EMT and oncogenic signaling." (PMID 30148686, 2019). "ELF3 is also amplified in 2–6% of tumours collectively suggesting a role in tumour progression." (PMID 30200227, 2018). "Next, we investigated the role of ELF3 in tumor growth in vivo." (PMID 29523781, 2018). "However, as discussed also in the previous paragraph, caution is needed in inhibiting ELF3, as the transcription factor may act as a tumor suppressor in certain contexts." (PMID 41425714, 2025). "Similarly, IL-1B, mostly secreted from tumor-associated macrophages as a pro-inflammatory cytokine, enhances the expression of ELF3 in LUADs with EGFR mutations, leading to the activation of the PI3K/Akt/NF-κB pathway and consequently contributes to tumor progression." (PMID 38983267, 2024). "This was expected as oncogene-enriched subtype tumours exhibited more aggressive tumour growth and had an increased expression of gene mutations involved in cell proliferation (ERBB2, SLC44A4, EPCAM, CLDN3, and CLDN4), cell differentiation (ELF3 and GPX2), and mucin production (KRT20)." (PMID 36723696, 2023). "In addition, ELF3 overexpression in 22RV1 xenografts resulted in larger and faster growing tumours." (PMID 35472129, 2022). "Neither the Longoni study nor the Shatnawi study used normal or benign cells as comparison controls in the biological studies, and each study used different cancer cell models; thus, conclusions were that ELF3 might be a tumour suppressor or oncogene, or it may be context and cell‐dependent." (PMID 35472129, 2022). "Therefore, FZD5 and ELF3 function as putative tumor suppressors in this type of cancer." (PMID 33618713, 2021). "Knocking down ELF3 expression attenuates activation of NF-κB pathway genes in two LUAD cell lines A549 (KRAS mutation) and NCI-H1975 (EGFR mutation L858R), supporting the conclusion that inflammatory cytokines (e.g. IL1B) can regulate tumor cell proliferation and anti-apoptosis through ELF3 action." (PMID 33144684, 2021). "In addition, as a potential oncogenic transcription factor, ELF3 promotes tumor cell growth and metastasis by modulating the PI3K/Akt and ERK pathways in NSCLC and may serve as a promising new target for the treatment of NSCLC patients." (PMID 30498398, 2018). "Finally, we validated the tumor-inhibitory roles of ELF3 using animal models." (PMID 28199976, 2017). "Mechanistically, we demonstrated that FKBP10 not only promoted EMT but also activated the MEK/ERK/ELF3 signaling axis, leading to an increased secretion of CXCL8 by tumor cells." (PMID 41694575, 2026). "Specifically, butyrate depletion in tumor-adjacent niches leads to HDAC-mediated hyperacetylation of the PDCD1 promoter, which is then recognized and bound by ELF3 and ATF4." (PMID 41438381, 2025). "Assessment of T cell-mediated antitumor responses in tumor tissues showed that knockdown of ELF3 increased CD8+ T cell infiltration and elevated the levels of TNF-α and IFN-γ in tumor tissue homogenates." (PMID 39219440, 2024). "The high expression of tumor-related genes (EPCAM, CD24, CDH1, ELF3, KRT18, KRT19, KRT8, and MUC1) in groups 10 and 11 suggests that cells in these groups are tumor cells." (PMID 38693422, 2024). "Knockdown of ELF3 in C666-1 cells slowed down tumor growth and reduced tumor burden, whereas overexpression of MUC16 promoted tumor growth instead." (PMID 39219440, 2024). "MUC16 overexpression reversed the repressive effect of ELF3 silencing on glycolysis and immune escape in NPC and accelerated tumor growth in vivo." (PMID 39219440, 2024).
tumor (continued). "We found that 25.0% intestine- and 37.8% esophagus-specific proteins, such as ELF3 and EPHA2, respectively, were upregulated in the tumor tissues, whereas 77.1% stomach-specific proteins, such as MUC5AC, were downregulated." (PMID 36788224, 2023). "ELF3 (E74-Like Factor 3) is an ETS transcription factor that exhibits context-dependent functionality, serving both as a lineage-dependent oncogene and as a tumor-suppressive gene." (PMID 38203275, 2023). "Based on transcription data from The Cancer Genome Atlas (TCGA), we identified four tumour-specific antigens for vaccine production: ARPC1B, ELF3, VSTM2L, and IL27RA." (PMID 37779866, 2023). "TFs, such as XBP1, TAF7, ELF3, MYC, MAX, etc., were more enriched in tumor cells of luminal BC than the other two subtypes." (PMID 36077333, 2022). "With IPMN progression, tumor stemness increased continuously, and KRAS, ERBB3, RUNX1, and ELF3 are essential driver genes affecting tumor stemness." (PMID 36090038, 2022). "We found that XBP1, TAF7, ELF3, MYC, MAX, etc., were more enriched in tumor cells of luminal BC than the other two subtypes." (PMID 36077333, 2022). "Interestingly, the effect of the tumor-activated versus control SCs on SCLC cell invasiveness was significantly higher, and this was associated with a higher level of expression of several genes, including the STAT3, SOCS3, BCL6, ELF3, IGF2, and IL32 genes, in SCLC cells." (PMID 36551618, 2022). "Intriguingly, NOTCH is required for tumor initiation in LUAD, and ELF3 is recruited to the NOTCH3 promoter via phosphorylation by protein kinase C iota (PKCί)." (PMID 34830169, 2021). "As observed in ELF3 knockdown or ANF treatment in vitro experiments in A549 and H1975 cells, cyclin A2, cyclin B1, and cyclin D1 were reduced in xenograft tumor tissues treated with ANF/GEF combination." (PMID 34830169, 2021). "However, the underlying mechanism of ELF3-mediated tumor suppression has not been elucidated." (PMID 33712555, 2021). "In summary, we detected six DEGs (RIPK4, SCNN1A, SLC4A11, ELF3, CLDN4, and SOBP) which can serve as tumor markers for the diagnosis and prognosis of OC." (PMID 33742531, 2021). "For instance, overexpression of ETV4, ELF3, and ETV5 facilitates tumor angiogenesis, growth, invasion and metastasis, and indicates poor prognosis." (PMID 33585247, 2020). "IHC revealed that expressions of ELF3, EHF and TGIF1 were higher in LUAD tumor tissues compared with peritumoral tissues." (PMID 33070167, 2020). "Remarkably, ELF3, EHF, and TGIF1 were highly expressed in LUAD tumor tissue compared with normal lung tissue, and the high expression of these TFs were positively correlated with poor prognosis in LUAD patients." (PMID 33070167, 2020). "Overexpression of ELF3 in CRC cells increased cell proliferation and transcription of β-catenin, suggesting a novel means of driving WNT signaling in these tumours." (PMID 30200227, 2018). "Increasing evidence indicates that transcription factors, such as IkBz, NF-kB, and ELF3 (E74-like factor 3), play crucial roles in the regulation of LCN2 expression in tumor cells of various origins, including lung and chondrocytes." (PMID 29098164, 2017). "We developed a four-gene expression signature (HIST1H2BG, SPP1, ELF3 and PCA3) with a sensitivity of 77 % and a specificity of 67 % (AUC = 0.763) for discriminating between tumor and control urines." (PMID 26856686, 2016). "Thus, ARPC1B, ELF3, VSTM2L, and IL27RA were identified as potential tumour antigens for mRNA vaccine production." (PMID 37779866, 2023). "Upon 5-FU and cisplatin treatment, ELF3-mediated transcription and secretion of SPINK1 increase, and potentiate HCC cells’ ability to promote tumor initiation, stemness, dedifferentiation and chemoresistance, by binding to EGFR and consequently driving the ERK-CDK4/6-E2F2 signaling cascade." (PMID 38030644, 2023). "Importantly, RA treatment induced expression of potential tumor-suppressive genes, HOXA5 and ELF3, also in the CSC-like cells." (PMID 36497371, 2022).